VIM (vimentin)
Diseases named in the same sentence as VIM in open-access papers (continued):
Sharing a sentence is not in itself a finding about the gene and the disease.
melanoma (continued). "We tested the impact of vimentin down-regulation (induced by PARP inhibition or vimentin silencing) on EMT differentiation in various melanoma cell lines and in endothelial cells." (PMID 23785295, 2013). "On the contrary, co-expression of keratin 8 and 18 together with vimentin leads to elevated invasion and cell migration in human melanoma." (PMID 23536778, 2013). "The same approach was used in B16F10 melanoma cells where over-expression of vimentin increased significantly cell migration." (PMID 23785295, 2013). "Our findings indicate that PARP inhibitors reduce the metastatic potential of melanoma cells, at least in part, through their ability to down-regulate vimentin expression." (PMID 23785295, 2013). "Within this cluster, however, most of the melanoma lines express VIM more strongly than CDH1, despite their low expression of migration-related genes." (PMID 22570691, 2012). "Neoplastic cells of the ocular neoplasm expressed Melan A and vimentin, similarly to those observed in domestic felines’ melanomas." (PMID 23009723, 2012). "In contrast, areas with epithelioid single cells expressed vimentin and Melan A, indicating melanoma cells." (PMID 23009723, 2012). "In a word, vimentin is not only the dignostic marker but also the hematogenous metastasis predictor for melanomas clinically." (PMID 20701774, 2010). "We further detected the expression of vimentin using immunohistochemistry in 70 primary malignant melanoma patients to evaluate its clinicopathological significance." (PMID 20701774, 2010). "In other words, vimentin is not only the dignostic marker but also the hematogenous metastasis predictor for melanomas clinically." (PMID 20701774, 2010). "There still have some studies which were concerning of aberrant overexpression of vimentin and its relationship with melanoma metastasis." (PMID 20701774, 2010). "Primary melanomas with overexpression of vimentin tends to have a more hematogenous metastasis incidence (P < 0.05)." (PMID 20701774, 2010). "Typically melanoma is reactive for vimentin, S-100 protein, HMB-45, melan -A, tyrosinase, and microphthalmia transcription factor." (PMID 17910749, 2007). "Notably, proteins associated with cell adhesion and mobility, such as VIM, CTTN, and LGALS3, are more abundant in melanoma cells." (PMID 40775377, 2025). "Similarly, in melanoma, GA upregulates E-cadherin, downregulates N-cadherin, Vimentin, MMP-2, and MMP-9, and enhances cell-matrix adhesion, forming a dual anti-invasive barrier that blocks EMT and invasion." (PMID 41311720, 2025). "Also, inhibiting CDC25A suppressed the EMT process of melanoma cells as evidenced by increased expression of E-cadherin, as well as decreased N-cadherin and vimentin expression." (PMID 40216745, 2025). "Once PLK1 was overexpressed, human melanoma cells exhibited an attenuated response to Vemurafenib treatment, along with the increased expression of metastatic markers N-Cadherin and Vimentin." (PMID 41284701, 2025). "In the present study, we also focus on the expression of Vimentin in melanoma." (PMID 39036079, 2024). "Along the trajectory, the gene signature of cluster 3 in melanoma cells was characterized as the activation of certain functional pathways, including the cell adhesion pathway (VIM), immune response signaling pathway (JUN, EGR1), and melanosome organization signaling pathway (MLANA)." (PMID 38862482, 2024). "Notably, SIRT1 expression is positively correlated with the EMT marker vimentin using Xiangya melanoma datasets and TCGA datasets." (PMID 39135915, 2024). "Vimentin, an intermediate filament protein found in mesenchymal cells, plays an essential role in regulating the motility and invasiveness of cancer cells, including melanoma cells." (PMID 37993880, 2023).
melanoma (continued). "Interestingly, in advanced melanoma models, TRPV2 also associates with the intermediate filament vimentin network, conceivably in order to extensively regulate cytoskeletal organization and adhesion structures mechanical maturation." (PMID 36744297, 2023). "Our study demonstrated that constitutive expression of YB-1 in melanoma seems to be tightly related to both nestin and vimentin expression which results in a stiffer phenotype, as well as a wide array of proteins involved in RNA, ribosomes, and spliceosome in A375 melanoma cell line." (PMID 39086667, 2023). "Furthermore, vimentin expression is correlated with the upregulation of N-cadherin, and it has been recently found that in melanoma, protein kinase C-iota (PKC-ι) activates vimentin while inducing EMT." (PMID 37511550, 2023). "In addition, morusin induces cell apoptosis and inhibits migration of melanoma cells, which correlated with the changes in the expression of the associated molecules including PARP, Caspase3, E-Cadherin and Vimentin." (PMID 37386395, 2023). "Moreover, vimentin, a major component of mesenchymal cells, was cleaved in drug-treated melanoma cells, suggesting disruption of their cytoskeletal structure and migration inhibition." (PMID 38020918, 2023). "CDK5 was found to regulate melanoma cell invasiveness by directly phosphorylating vimentin." (PMID 37993880, 2023). "In addition, VIM, TTR, and TYR genes were used to evaluate the diagnosis of melanoma, which suggested VIM and TYR involved in pigment synthesis, and the mechanism of action needs further study." (PMID 37402463, 2023). "K8/18- and vimentin-expressing melanomas are more invasive than those expressing only vimentin." (PMID 35330094, 2022). "Indeed, RNA sequencing, ribosomal profiling, and iCLIP sequencing suggested that CSDE1 regulated pro-metastatic factor RNA regulons and mediated invasion and metastasis by regulating translation elongation of vimentin and Rac1 mRNA in melanoma." (PMID 35490208, 2022). "Besides, CSDE1 was also verified to have tumor-promoting effects in melanoma by regulating the translation of vimentin and Rac-1." (PMID 35923244, 2022). "Thus, female melanoma cells with high expression of ERβ show a reduction in N-Cadherin, vimentin, Snail, and Zeb1 and characteristically a parallel increase in PTEN expression; while in the ERβ silencing experiments, markers of EMT rise and PTEN decreases." (PMID 36499700, 2022). "Previous studies showed that melanoma cells might be hindered in accelerating invadopodia activity, and subsequently, Vimentin was suppressed." (PMID 36238547, 2022). "Indeed, one of the transcriptional targets of Slug is the ZEB1 protein, which is capable of directly activating the transcription of N-cadherin and vimentin in melanoma." (PMID 36429073, 2022). "After co-cultivating normal human epidermal melanoma cell lines with exosomes derived from melanoma cells, E-cadherin was significantly downregulated compared with normal cell epithelial cells, whereas the mesenchymal marker vimentin was significantly upregulated." (PMID 34485600, 2021). "Vimentin staining revealed enlarged cells, which is consistent with a report showing that loss of MITF affects the cytoskeletal structure and shape of melanoma cells." (PMID 33438577, 2021). "LAM cells consist of two types of cell subpopulations, fibromyoblast-like spindle-shaped cells which express smooth muscle specific proteins (e.g. α‐actin, desmin, vimentin) and epithelioid-like cells which express glycoprotein gp100, a marker of melanoma cells and immature melanocytes." (PMID 33119872, 2021). "In the present study, enforced PEAK1 inhibited E-cadherin expression, and promoted vimentin expression and PEAK1 knockdown promoted E-cadherin expression, and reduced vimentin expression in melanoma cells, suggesting that PEAK1 is associated with invasion and metastasis through regulating EMT." (PMID 34365903, 2021).
melanoma (continued). "p32 silenced B16F10 cells subcutaneous tumors showed decreased proliferation (Ki-67), angiogenesis (CD34), leukocyte (CD45), macrophage (F4/80) markers, and vimentin expression than control tumors confirming its involvement with p32-mediated melanoma tumor progression." (PMID 34711805, 2021). "Vimentin and S100 protein positivity was detected in all melanoma samples." (PMID 33535453, 2021). "We detected vimentin as an upregulated protein in the melanoma samples." (PMID 34206844, 2021). "Attenuation of vimentin expression by HopQ inhibited melanoma motility and in vivo metastasis." (PMID 32286254, 2020). "Also, human melanoma black (HMB-45), Vimentin, and Melan A antibody are the melanocyte specific stains used for diagnosis of malignant melanoma." (PMID 32000450, 2020). "In conclusion, this work suggests that a bacterial effector protein HopQ, which effectively removes vimentin from melanoma cells, may act as a novel therapeutic target for the treatment of metastatic melanoma." (PMID 32286254, 2020). "We also investigated the correlation of the seven prognostic-associated TBCs between MMP-related genes (MMP2, MMP9, MMP7, MMP14, BSG, EGFR, MMP1, MMP3) and EMT-associated genes (TWIST1, VIM, CDH2, ACTA2, ZEB1), which also indicated a central role of TBCs in melanoma." (PMID 33194704, 2020). "Finally, immunohistochemical examination with HMB-45, S-100, and Vimentin staining was positive for melanoma in all patients with pathological diagnosis of anorectal melanoma." (PMID 28412758, 2017). "Furthermore, the combination treatment was more effective than individual agents in reducing expression of N-cadherin, vimentin and fibronectin mesenchymal marker proteins in melanoma xenografts implanted with A375 and SK-MEL-28 cells." (PMID 26517521, 2016). "In order to verify whether the tumor-conditioned media from breast ductal adenocarcinoma AU-565 and melanoma Hs 852.T cells altered myoepithelial cell morphology, the cells were examined using indirect immunofluorescence for vimentin." (PMID 25435982, 2015). "We also demonstrated that vimentin expression was sufficient to induce increased mesenchymal/pro-metastasic phenotypic changes in melanoma cells, including ILK/GSK3-β-dependent E-cadherin down-regulation, Snail1 activation and increased cell motility and migration." (PMID 23785295, 2013). "The results presented here indicates that PARP inhibition, through down-regulation of the intermediary filament vimentin in both endothelial and melanoma cells, led to a reversion of mesenchymal phenotype in both cell types and prevented malignant melanoma cells from developing vasculogenic mimicry." (PMID 23785295, 2013). "So it is merely a hypothesis that vimentin involving in the melanoma metastasis is by EMT progression." (PMID 20701774, 2010). "The aberrant immunohistochemistry expression of vimentin in primary melanoma tissues may help to call attention for patients with high risk of hematogenous metastasis." (PMID 20701774, 2010). "Generally, vimentin is usually used as a marker to diagnose human melanoma clinically." (PMID 20701774, 2010). "Our results showed that increased expression of vimentin might be as a novel metastatic indicator for melanoma." (PMID 20701774, 2010). "The aberrant immunohistochemical expression of vimentin in primary melanoma tissues may help to call attention for patients with high risk of hematogenous metastasis." (PMID 20701774, 2010). "The most valuable significance of our study is to discover that vimentin might be served as a potential biomarker for predicting the melanoma hematogenous metastasis by using one set of clinical samples." (PMID 20701774, 2010). "Whereas vimentin positivity as in this case, occurs also in high malignant melanomas." (PMID 17227576, 2007).
melanoma (continued). "At the molecular marker level, GA exhibits bidirectional regulation: in bladder cancer and melanoma models, it restores intercellular adhesion by upregulating the epithelial marker E-cadherin while significantly downregulating mesenchymal markers N-cadherin and Vimentin." (PMID 41311720, 2025). "Indeed, melanoma cells ubiquitously express high levels of the mesenchymal marker Vimentin." (PMID 40754577, 2025). "Furthermore, VIM could be used as one of the marker proteins for diagnosis of malignant melanoma, and it was found to be involved in the synthesis of melanin." (PMID 37402463, 2023). "Therefore, regulating the intracellular content of vimentin may be a practical approach to interfere with melanoma metastasis." (PMID 32286254, 2020). "Additionally, erlotinib also antagonized LRIG1 knockdown-induced decrease in E-cadherin and increase in vimentin in hypoxia-stimulated melanoma cells, indicating that LRIG1 depression could enhance hypoxia-induced EMT by activating the EGFR/ERK pathway." (PMID 30487162, 2019). "On the whole, we first demonstrated the significant upregulation of vimentin in metastatic melanoma compared to primary cases by proteomics and carried out the clinical verification to evalute whether vimentin is a potential biomarker for predicting the metastasis in melanoma patients." (PMID 20701774, 2010). "IHC studies showed positivity for vimentin and Melan-A and negativity for CD117 and S100, confirming the diagnosis of melanoma." (PMID 41280416, 2025). "These regulators include MAPK signaling pathway indicators p-BRAF and p-ERK, metastatic markers N-Cadherin and Vimentin, proliferative marker PCNA, and melanoma-specific transcription factor SOX10." (PMID 41284701, 2025). "After iEV-150 coculture, E-cadherin expression increased, whereas N-cadherin and vimentin expression decreased, suggesting the inhibition of epithelial‒mesenchymal transition (EMT) in melanoma cells." (PMID 40860143, 2025). "In vitro studies demonstrated that curcumin exhibited a dose-dependent suppression of IDO expression in B16 melanoma cells, effectively preventing the process of EMT by reducing vimentin expression and restoring E-cadherin expression." (PMID 40918451, 2025). "The results illustrated that Artemisinin significantly decreased the expression of Snail, N-cadherin and Vimentin while increasing the expression of E-cadherin, supporting that Artemisinin was able to suppress EMT to inhibit melanoma migration and invasion." (PMID 39744440, 2025). "Rectal immunohistochemical detection: CK EMA (-) (-), Vimentin (+) S - 100 (+) oven HMB 45 (+) - (+) the SOX Melan - A - 10 (+) about (-) CK56 P40 (-) (-) Ki - 67 (+ 70%), in accordance with melanoma." (PMID 40900782, 2025). "Histological markers used to diagnose melanoma are: S100 protein, HMB45, Melan-A, Tyrosinase, MITF and Vimentin." (PMID 39862670, 2025). "Key immunohistochemistry markers for diagnosing malignant melanoma include HMB-45, S-100, melan A, and vimentin." (PMID 39449907, 2024). "Melanoma of the urinary bladder stains positively for S100, HMB45, SOX10, and negatively for keratin and vimentin consistent with our patient’s positively stained immunohistochemistry." (PMID 38933829, 2024). "Conversely, decreased E‐cadherin and increased vimentin and SNAL1 protein levels were detected in USP22‐overexpressing melanoma cells." (PMID 39135915, 2024). "When miR-22-3p is overexpressed in WM-266-4 melanoma cells, the cell viability is decreased, the expression levels of LGALS1, VIM, and SNAI2 are decreased, the expression level of CDH1 is increased, and cell apoptosis is increased." (PMID 39684214, 2024). "Immunohistochemical markers such as vimentin, HMB-45, and S-100 are crucial in the final diagnosis and differentiating these melanomas from epidermoid carcinomas." (PMID 39036271, 2024). "We found that E-cadherin and GSK-3β were up-regulated while vimentin and β-catenin were downregulated in si-LINC00662 melanoma cells." (PMID 38169586, 2024).
melanoma (continued). "The expression of E-cadherin/Vimentin/CD80/CD155 proteins in cSCC, HNSCC and melanoma patient samples predicts response to anti-PD-1/PD-L1 therapy." (PMID 38914547, 2024). "Immunohistochemical analysis revealed positive reactions for S-100 protein, antihuman melanoma black-45 (HMB-45) antibody, vimentin (VIM), Sox-10, melan-A, vascular endothelial growth factor, and glial fibrillary acidic protein." (PMID 39495986, 2024). "In melanoma and head and neck squamous cell carcinoma, Notch4 signalling induces EMT by stimulating the expression of EMT markers such as Vimentin and Twist1 and downregulating the expression of E-cadherin." (PMID 37108670, 2023). "We included lysates of the melanoma MEWO and prostatic cancer DU145 cell lines as positive controls for vimentin and cytokeratin expression." (PMID 35681572, 2022). "Melanoma cells (HMB‐45), fibroblast (α‐SMA), ICAM‐I, vimentin and immune cells (CD45+ and CD3+ T cells) presented in the MPDOs by immunocytochemistry." (PMID 35731974, 2022). "SIRT1 induces epithelial-mesenchymal transition (EMT) in melanoma cells by down-regulating E-cadherin (CDH1) and up-regulating N-cadherin (CDH2) and vimentin (VIM)." (PMID 36139919, 2022). "So far, our data reveal that the expression levels for clathrin, vimentin, and SNX9 increased during TRPV4 activation induced exocytosis in human melanoma A375 cells." (PMID 35456964, 2022). "Immunohistochemistry is mainly used to assist in the identification of melanoma in pathological examination; for example, S-100, HMB-45, and vimentin are sensitive indicators for the specific diagnosis of melanoma." (PMID 35356202, 2022). "It has been found that the regulation of VIM and RAC1 mRNA translation by CSDE1 contributes to melanoma metastasis." (PMID 36354136, 2022). "Vimentin, a frequently used marker for EMT, showed increased expression in the RF-FTMs, especially in both the AN and M14 melanoma FTMs as a strong positive staining throughout the invasive area in the reticular dermal compartments was observed." (PMID 36232952, 2022). "In our recently published work, we screened several melanoma and carcinoma cell lines (MV3, SCL‐1, SCL‐2, BLM, patient‐derived HNC cells) and targets (MCSP, EpCAM, cell surface vimentin) to find a suitable candidate for the testing of microfluidic platforms." (PMID 35573135, 2022). "Also, AMBRA1 expression negatively correlated with the expression of the mesenchymal genes CDH2, FN1 and VIM, whereas a positive correlation was evident for the epithelial marker CDH1, hence suggesting that an active EMT-like process is associated with low AMBRA1 expression in human melanoma cells." (PMID 33953176, 2021). "Our previous reports on melanoma confirmed that TGFβ stimulated Smad2/3 and Par6/PKC-ι/RhoA pathways stimulated the expression of PKC-ι along with Vimentin." (PMID 33525953, 2021). "Melanoma cells were treated with TNF-α in a 3-dimensional culture system, and the changes in the expression of E-cadherin, N-cadherin, vimentin, and fibronectin were assessed." (PMID 33986746, 2021). "Melanoma cells treated with TNF-α reduced the epithelial marker E-cadherin and induced mesenchymal markers N-cadherin, vimentin, fibronectin." (PMID 33986746, 2021). "For instance, WNT5a increased Vimentin expression, but also decreased E-cadherin via activation of PKC pathway in melanoma cells." (PMID 32546756, 2020). "Once MDSCs were depleted, the expression of S100A4 and Vimentin which downregulated the expression of E-cadherin and promoted EMT would be decreased in a murine melanoma model." (PMID 32092078, 2020). "In our studies, we showed that alteronol effectively inhibits melanoma cells EMT as the upregulation of E-cadherin and down-regulation of vimentin." (PMID 32265437, 2020). "In addition, we determined whether HopQ decreases vimentin levels in human melanoma cell lines." (PMID 32286254, 2020).